LINC01508 (long independently transcribed non-coding RNA 1508)
Gene: Long non-coding RNA gene on chromosome 9 (90,300,885 to 90,433,684, reverse strand). Ensembl gene ENSG00000231107.
Diseases named in the same sentence as LINC01508 in open-access papers:
LINC01508 is named in the same sentence as 2 diseases in open-access papers, as found by Europe PMC text mining. Sharing a sentence is not in itself a finding about the gene and the disease. The quoted sentences say what the papers report.
ovarian carcinoma (1 paper, 2022). A malignant neoplasm originating from the surface ovarian epithelium. "Moreover, the downregulation of LINC01508, a long noncoding RNAs, contributes to cisplatin resistance in ovarian cancer." (PMID 36146599, 2022).
LINC01508 also shares sentences with these, for which no sentence is quoted: coronary artery disease (1 paper).